RUNX3 (RUNX family transcription factor 3)
Diseases named in the same sentence as RUNX3 in open-access papers (continued):
Sharing a sentence is not in itself a finding about the gene and the disease.
breast carcinoma (continued). "RUNX3 expression led to down-regulation of the ER protein and suppression of ER mediated transactivation and cancer cell proliferation in multiple breast cancer cell lines." (PMID 36831308, 2023). "The PIN1 WW domain binds to four pSer/Thr-Pro residues (T209, T212, T231 and S214) on RUNX3, resulting in the ubiquitination and degradation of RUNX3 in breast cancer." (PMID 36899853, 2023). "Restoration of RUNX3 expression through retroviral vectors in MCF7 breast cancer cells, where RUNX3 is naturally hypermethylated, has been shown to inhibit proliferation and clonogenic potential of the gene in both in vitro and in vivo models." (PMID 36831308, 2023). "Mechanistically, RUNX3 inhibits estrogen-dependent proliferation and oncogenic potential of ERα-positive breast cancer cells by reducing the stability of ERα protein." (PMID 36766749, 2023). "RUNX3 is predominantly characterized as a tumor suppressor and is frequently inactivated in many cancers, including gastric, lung, and breast cancer." (PMID 36899853, 2023). "While many studies provide evidence for RUNX3 in breast cancer suppression, we note that others have discussed the expression status of this transcription factor in some epithelial lineages." (PMID 36831308, 2023). "In breast cancer patients, the proportion of RUNX3‐positive stromal fibroblast‐like cells tends to be higher in cancerous regions than in non‐cancerous regions." (PMID 37641472, 2023). "DNMT1-regulated hypermethylation of the TSG RUNX3 promoter region is a new insight and an early event in breast cancer predominantly in TNBC (triple-negative breast cancer)." (PMID 35898303, 2022). "Depletion of RUNX2 had a stronger inhibitory effect on the proliferation of breast cancer cells than the suppression of RUNX1 or RUNX3." (PMID 35534547, 2022). "Some studies founded that RUNX3 is inactivated in several tumors including breast cancer and it is identified as a tumor suppressor to reduce the initiation and progression of breast cancer." (PMID 36092942, 2022). "RUNX3 inhibits estrogen-dependent proliferation by targeting ERα in breast cancer cell lines and functions as a tumor suppressor, but its role has not been defined." (PMID 35906698, 2022). "One such tumor suppressor gene (TSG) RUNX3 (Runt-related transcription factor 3) has been a new insight in breast cancer known to be suppressed due to local promoter hypermethylation mediated by DNA methyltransferase 1 (DNMT1)." (PMID 35898303, 2022). "So far, the individual role of RUNX3 as a TSG in breast cancer and DNMT1 as the methylation maintenance protein has been reported in various scientific studies." (PMID 35898303, 2022). "Non-coding RNAs that target RUNX3 in breast cancer have been previously identified, suggesting that further investigation of the role of RUNX3 in chemoresistance and its regulation in breast cancer is justified." (PMID 33918859, 2021). "HDAC5 increased the stemness of human breast cancer stem cells through inhibiting the binding of the Runt-related transcription factor 3(RUNX3)/p300 complex to the promoter of target genes." (PMID 34178647, 2021). "The promoter region of RUNX3 is hypermethylated, resulting in its decreased expression in breast cancer." (PMID 34485309, 2021). "Through analysis of the TIMER database, we found that RUNX1 had highly frequent mutations in breast cancer, while RUNX2 and RUNX3 had a lower frequency of mutation rate." (PMID 34485309, 2021). "A previous study has shown that promoter methylation contributes to RUNX3 inactivation in breast cancer." (PMID 34485309, 2021). "We found that the methylation level changes of RUNX2 and RUNX3 had opposite effects on immune cell infiltration in breast cancer." (PMID 34485309, 2021). "RUNX family transcription factor 3 (RUNX3) is reported to act as a tumor suppressor in breast cancer and lung cancer." (PMID 34336665, 2021).
breast carcinoma (continued). "RUNX3 destabilizes estrogen receptor alpha and suppresses its transcriptional activation, thus supporting its tumor-suppressive role in breast cancer." (PMID 34485309, 2021). "On the other hand, several studies demonstrated RUNX3 inhibition in different cancers, such as colorectal cancer, glioma, melanoma, and breast cancer." (PMID 33924679, 2021). "We found that the methylation level of RUNX3 in breast cancer is completely opposite to that of RUNX1 and RUNX2." (PMID 34485309, 2021). "With RUNX3, inactivation and protein mislocalization occur during the early stages of breast cancer progression." (PMID 34485309, 2021). "RUNX3 is frequently inactivated in human breast cancer cell lines and cancer samples by homozygous deletion of the RUNX3 gene, hypermethylation of the RUNX3 promoter, or cytoplasmic sequestration of the RUNX3 protein." (PMID 32771023, 2020). "We have previously shown that TrkB promotes tumorigenesis and metastasis in breast cancer via the suppression of RUNX3 expression." (PMID 32731498, 2020). "The Kaplan-Meier survival analysis revealed that the breast cancer patients with low expression of RUNX3 had a shortened OS compared to those with high expression." (PMID 32771023, 2020). "The nuclear dislocation of RUNX3 disabled this tumour suppressor and led to breast cancer cells gaining stem cell–like traits." (PMID 32307917, 2020). "Here, in this work, our group also reported this phenomenon that cytoplasmic RUNX3 retention indicated poor prognosis in breast cancer, further highlighting the possible oncogenic role of cytoplasmic RUNX3." (PMID 32307917, 2020). "As RUNX3 is located in 1p36, a region often deleted in breast cancer, we focus this study on the regulatory role of this transcription factor." (PMID 32771023, 2020). "Next, we sought to further clarify the expression pattern of PIM1 and RUNX3 in breast cancer tissues." (PMID 32307917, 2020). "Pin1 recognizes four phosphorylated Ser/Thr-Pro motifs in RUNX3 via its WW domain to suppress the transcriptional activity of RUNX3 and induce the ubiquitination and proteasomal degradation of RUNX3 in breast cancer." (PMID 32296699, 2020). "Inhibition of PIM1 significantly induced the nuclear retention of RUNX3, recovered its transcriptional function and attenuated the stem cell–like properties of breast cancer cells." (PMID 32307917, 2020). "We then performed immunohistochemical analysis to evaluate the potential association between RUNX3 and RCAN1.4 protein levels in breast cancer samples." (PMID 32771023, 2020). "The results showed that low mRNA expression of RUNX3 was associated with poor OS, RFS, and early distant metastasis-free survival (DMFS) in breast cancer patients." (PMID 32771023, 2020). "RUNX3 expression in breast carcinoma tissues was significantly lower than that in matched normal breast tissues." (PMID 32771023, 2020). "The breast cancer patients with tumours that had low mRNA expression of both RUNX3 and RCAN1.4 had significantly shorter overall survival than those with tumours that were categorized as “others”." (PMID 32771023, 2020). "Despite this emergent role of RUNX1 and RUNX3 as tumor suppressors in breast cancer, the mechanistic details regarding how they exert their tumor suppressor function in breast cancer is yet to be understood." (PMID 29581836, 2018). "Here, we identify RUNX1 and RUNX3 as novel negative regulators of oncogenic function of YAP in the context of breast cancer." (PMID 29581836, 2018). "Out of the three RUNX proteins, RUNX1 and RUNX3 have been recently identified as novel tumor suppressors in breast cancer." (PMID 29581836, 2018). "Analysis of whole genome expression profiles of breast cancer samples revealed significant co-relation between YAP–RUNX1/RUNX3 expression levels and survival outcomes of breast cancer patients." (PMID 29581836, 2018).
breast carcinoma (continued). "The novel interplay between YAP, RUNX1 and RUNX3 and its significance in breast cancer progression can serve as a prognostic tool to predict cancer recurrence." (PMID 29581836, 2018). "To investigate physiological relevance of YAP-RUNX interaction in the context of breast cancer progression, we tested effect of co-expression of RUNX3 on YAP-mediated pro-tumorigenic transformation of mammary epithelial cells." (PMID 29581836, 2018). "Runt-related transcription factor 3 (RUNX3) methylation plays an important role in the carcinogenesis of breast cancer (BC)." (PMID 27825140, 2017). "Previous reports have shown that RUNX3 expression was reduced in numerous types of human cancers, such as breast cancer, colorectal cancer, renal cell carcinoma, melanoma." (PMID 24475196, 2014). "For instance, functional inactivation of RUNX3, a tumor suppressor, is frequently observed in various types of cancer, including glioma and breast cancer." (PMID 23708493, 2013). "Expression of Pin1 inversely correlates with the expression of RUNX3 in human breast cancer samples." (PMID 23708493, 2013). "It has been convincingly demonstrated that RUNX3 acts as a tumor suppressor in breast cancer, and that it modulates the function of ERα." (PMID 23704974, 2013). "The RUNX3 gene is located on chromosome 1 at 1p36, a locus that is frequently disrupted in breast cancer." (PMID 23704974, 2013). "For example, RUNX3 is a transcription factor with tumor suppressor activity that is mislocalized to the cytoplasm in breast cancer." (PMID 24223206, 2013). "Nuclear expression in breast cancer cell lines results in decreased invasiveness in vitro and decreased tumorigenesis in vivo, suggesting that cytoplasmic localization prevents RUNX3 from acting as a tumor suppressor." (PMID 24223206, 2013). "Mislocalisation of RUNX3 protein to the cytoplasm is another mechanism by which RUNX3 can be inactivated in gastric and breast cancers." (PMID 19223906, 2009). "RUNX3 was enriched in hc7, which is a critical transcription factor playing essential roles in development and carcinogenesis and has been frequently reported to be a tumor suppressor in breast cancer through diverse mechanisms." (PMID 38472225, 2024). "RUNX3 functions as a tumor suppressor in breast cancer and is frequently inactivated by promoter hypermethylation and protein mislocalization, and expression of RUNX3 has been suggested as a promising prognostic biomarker in breast cancer patients." (PMID 36899853, 2023). "Furthermore, to investigate an association of stromal RUNX3 expression with the prognoses in breast cancer patients, tumor sections prepared from 241 breast cancer patients were stained with an anti‐RUNX3 antibody and subjected to tissue microarray analysis." (PMID 37641472, 2023). "To examine whether RUNX3 expression is upregulated in tumor‐associated stroma of breast cancer patients, we performed immunohistochemical staining of patient tumor sections using antibodies against α‐SMA and RUNX3." (PMID 37641472, 2023). "Considering the results of xenografts and patient tissue microarray together, it is possible that while overexpression of RUNX3 in CAFs contributes to tumor proliferation, it does not promote metastasis, the major cause of death in breast cancer." (PMID 37641472, 2023). "Interestingly, gene expression profiling of primary breast cancer stromal cells identified RUNX3 as part of a 26-gene signature that was correlated to poor clinical outcome." (PMID 36831308, 2023). "In addition, consensus sequences of RUNX3 is enriched at the binding sites in the SE region of RCAN1.4 in breast cancer." (PMID 37032358, 2023). "Moreover, we demonstrated that the downregulation of RUNX3 expression in the exp‐CAFs suppresses the growth of xenograft tumors generated from co‐implantation of the exp‐CAFs and breast cancer cells in vivo." (PMID 37641472, 2023).
breast carcinoma (continued). "Moreover, our findings advocate DNMT1 as a potential epigenetic drug target to revive the suppressed TSG RUNX3 in breast cancer therapeutics." (PMID 35898303, 2022). "Moreover, several former studies have reported the depleted level of RUNX3 in breast cancer cell lines predominantly due to local hypermethylation at the proximal promoter region of TSG RUNX3, which is an early event in carcinogenesis." (PMID 35898303, 2022). "In breast cancer, the prolyl isomerase Pin1 recognizes the four phosphorylated Ser/Thr-Pro motifs in RUNX3 through its WW structural domain, thereby cis-trans-isomerizing the proline amino-terminal bond and downregulating the transcriptional activity of RUNX3." (PMID 36429115, 2022). "It was discovered that RUNX3 acts as a tumor suppressor gene in breast cancer." (PMID 34367349, 2021). "Interestingly, we also found opposite effects of RUNX2 and RUNX3 gene methylation changes on immune cell infiltration in breast cancer." (PMID 34485309, 2021). "Similarly, we also used the UALCAN database to further analyze the expression levels of RUNX2 and RUNX3 in breast cancer." (PMID 34485309, 2021). "We confirmed in our work that RUNX3 could attenuate the stem cell–like traits in breast cancer cells and mediate the antitumour effects of PIM1 inhibition in this way." (PMID 32307917, 2020). "All these clinicopathological results suggested that RUNX3 dislocation may mediate the tumorigenic effects of PIM1 in breast cancer." (PMID 32307917, 2020). "In brief, PIM1 could enhance the stem cell–like traits of breast cancer cells by promoting the phosphorylation and cytoplasmic localization of RUNX3." (PMID 32307917, 2020). "Emerging evidence indicates that RUNX3 is a tumour suppressor in breast cancer." (PMID 32771023, 2020). "In this study, we revealed that inhibition of PIM1 kinase could attenuate the stem cell–like traits in breast cancer by rescuing the nuclear expression of RUNX3." (PMID 32307917, 2020). "Runt-related transcription factor 3 (RUNX3) is an ERα inhibitor in breast cancer." (PMID 32296699, 2020). "All these results suggested that PIM1 could promote the EMT process of breast cancer cells and this effect could be attenuated by RUNX3 and reversed by RUNX3(4A)." (PMID 32307917, 2020). "We demonstrated that PIM1 could phosphorylate RUNX3 to facilitate its cytoplasmic retention, thus suppressing the transcriptional activity of RUNX3 and promoting breast cancer to gain BrCSC‐like traits." (PMID 32307917, 2020). "And this implied us that PIM1 might exert both its pro‐BrCSC and pro‐EMT effects by phosphorylating RUNX3 due to the fact that breast cancer cells could gain stem cell–like traits by undergoing EMT process." (PMID 32307917, 2020). "Besides, PIM1 was shown by our results to co‐localize with and directly bind with RUNX3 in cytoplasm of breast cancer cells." (PMID 32307917, 2020). "In addition, we also analysed the prognostic value of combining RCAN1.4 and RUNX3 protein levels in breast cancer samples." (PMID 32771023, 2020). "We thus sought to investigate the role of PIM1 and RUNX3 in EMT process of breast cancer cells." (PMID 32307917, 2020). "RUNX3, a tumor suppressor in breast cancer, has been identified as a Pin1 substrate." (PMID 32266261, 2020). "However, RUNX3 has also been indicated as a tumor suppressor in breast cancer, which needs further careful evaluation." (PMID 31075939, 2019). "Given that RUNX1 and RUNX3 interact with YAP and co-regulate transcription, we investigated whether RUNX1-RUNX3 interaction with YAP has biological significance in the context of breast cancer." (PMID 29581836, 2018). "Given the recent discovery of RUNX1 and RUNX3 as tumor suppressors in the context of breast cancer and their known interaction with oncogene-YAP, we investigated whether YAP-RUNX interaction plays any role in molecular pathogenesis of breast cancer." (PMID 29581836, 2018).
breast carcinoma (continued). "Furthermore, our recent report that CADD522 activates theHippo tumor suppressor pathway in luminal breast cancer suggests a compensatory pathway to overcome the potential drawback of RUNX3 inhibition by CADD522." (PMID 29050333, 2017). "Both RUNX1 and RUNX3 have tumor suppressor roles in breast cancers, while RUNX2 is tumor-promoting." (PMID 28412963, 2017). "Up-regulation of miR-130a could affect the doxorubicin resistance in breast cancer, and miR-130a induced the resistance of liver cancer cell to cisplatin by downregulation of tumor suppressor gene RUNX3." (PMID 26043084, 2015). "Study had demonstrated that RUNX3 could inhibit the transcriptional activation of ERα and function as a tumor suppressor in the Runx3+/− female mice breast cancer model." (PMID 25298284, 2014). "The result of this search suggested that perhaps RUNX3, which is capable of modulating ER transcriptional activity and stability, could also play a role in the generation of ER+ versus ER− breast cancers." (PMID 23704974, 2013). "Combined with the ability of RUNX3 to impinge upon estrogen receptor function, these data suggest that RUNX3 could play a potentially significant role in the development of ER+ breast cancer in vivo." (PMID 23704974, 2013). "Collectively, our xenograft experiment results suggest that RUNX3 expression in CAFs could contribute to the promotion of tumor growth, at least, through stimulating the tumor cell proliferation and blood vessel formation in human breast cancer." (PMID 37641472, 2023). "In addition, a further research was made on the functions of high risk immune gene ULBP2 and low risk immune gene TRDV1 which regulated by RUNX3, the results showed that down-regulation of ULBP2 suppressed breast cancer cell proliferation and TRDV1 had the opposite functions." (PMID 36092942, 2022). "However, despite the evident role of RUNX3 in breast cancer and the relation of DNMT1 with RUNX3 gene, no study has explored the underlying epigenetic molecular events by which DNMT1 silences RUNX3 to promote breast cancer metastasis." (PMID 35898303, 2022). "Consequently, designing specific small modulators that inhibit DNMT1 activity in order to restore the TSG RUNX3 could represent new clinical avenues for breast cancer therapeutics." (PMID 35898303, 2022). "RUNX3 may also be related to chemoresistance in breast cancer." (PMID 33918859, 2021). "Therefore, Pin1-mediated protein degradation might partially account for the decreased RUNX3 expression, an early event in breast cancer progression." (PMID 32266261, 2020). "However, the role of RUNX3 in breast cancer stem cell was barely mentioned." (PMID 32307917, 2020). "However, molecular basis of tumor suppressor function of RUNX1 and RUNX3 in breast cancer is largely unknown." (PMID 29581836, 2018). "Hence, we chose breast cancer cell lines other than MDA-MB-231 to confirm whether RUNX3 mediated inhibition of tumorigenic phenotypes depends on the level of YAP expression." (PMID 29581836, 2018). "This antagonistic activity of RUNX1 and RUNX3 towards oncogenic function of YAP identified in mammary epithelial cells as well as in breast cancer expression profiles gives a novel mechanistic insight into oncogene–tumor suppressor interplay in the context of breast cancer progression." (PMID 29581836, 2018). "Additionally, nearly 50% of human breast cancers do not express RUNX3 and loss of expression is associated with ER positivity." (PMID 23704974, 2013). "miR-210 participates in the proliferation of breast cancer cells, particularly triple-negative cells, and is related to lymph node metastases through targets such as CCND1 and RUNX3." (PMID 38813102, 2024). "miR-600 has the capability to impede the malignant behavior of breast cancer cells and enhance their sensitivity to sorafenib through the EZH2/RUNX3 axis." (PMID 38807590, 2024).